ESR1 (estrogen receptor 1)
Diseases named in the same sentence as ESR1 in open-access papers (continued):
Sharing a sentence is not in itself a finding about the gene and the disease.
breast cancer (continued). "Also, no mutations were detected for other described breast cancer‐associated genes (e.g., RAD51, RAD50, p27, ESR1/2, ERBB2, ERBB3, AKT1, CCDN1, FGFR1, MYC, and RB1) in any of the tissues or the CTC cell line." (PMID 32667137, 2020). "These genes, like ESR1, which have a significant role in breast cancer etiology, could not be investigated in our study." (PMID 32079541, 2020). "This analysis revealed that in general, ESR1 expression exhibits a negative correlation with FAM171A1 in breast cancer datasets, and a similar trend was also observed for PGR in respective cell lines as well as carcinoma databases other than breast cancer datasets." (PMID 30631046, 2019). "Additionally, we further explored the relative gene expression of other important hormonal receptors in breast cancer, such as estrogen receptor beta (ESR2), progesterone receptor (PGR) and androgen receptor (AR), concomitantly with estrogen receptor alpha (ESR1)." (PMID 31817155, 2019). "Our finding that PR-deficient cells show lower ER levels compared to control cells suggests that the ER+/PR+ breast cancers are more likely to respond to SERM therapy because they could maintain the ESR1 levels higher than breast cancers without PR protein." (PMID 30301163, 2018). "Although the methods for detecting ESR1 or HER2 in breast cancer biopsies by immunohistochemistry are well established, AR immunohistochemistry performed on tumor biopsies is not routine or standardized leading to a wide variation in the reported number of AR-positive breast cancer cases." (PMID 30279965, 2018). "To examine the pathological and clinical features associated with cfDNA ESR1 and PIK3CA mutations in the 113 ER + /HER-cases, we looked at differences in the clinical features of the breast cancer between patients who had and did not have detectable ESR1 or PIK3CA mutations in cfDNA." (PMID 30083595, 2018). "Furthermore, while ESR1 can initially upregulate AGR2 expression, breast cancer cells that achieve tamoxifen resistance no longer require ESR1 for AGR2 expression, likely due to an alteration in the activity of the transcription factor FOXA1." (PMID 29796176, 2018). "Breast cancer is a heterogeneous disease that is classified into three subtypes: luminal, human epidermal growth factor receptor 2 (HER2)-enriched, and basal-like based on the presence of ERα (coded by the ESR1 gene), progesterone receptor (coded by the PGR gene) and HER21." (PMID 30375428, 2018). "We found that TF expression in breast cancer lines and tumors closely clustered with higher levels of EMT (high vimentin/low E-cadherin) and classical basal-type biomarkers KRT5, KRT14 and caveolin-1, while it clustered with lower levels luminal-type biomarkers KRT8, KRT18, ERBB3 and ESR1." (PMID 28938620, 2017). "Notably, we found that only a subset of patients with clinically diagnosed HR+ breast cancer expressed ESR1 in CTCs and ESR1 expression was in all cases absent after initiation of endocrine treatment or chemotherapy." (PMID 28489591, 2017). "Patients were grouped according to whether or not cfDNA ESR1 mutations increased, and groups were compared by the patient response end points of time-to-treatment failure (TTF) and breast cancer-specific survival (BCSS)." (PMID 27102299, 2016). "Barx2 increased expression of both ESR1 isoforms, the estrogen-responsive genes (SOX5, RBM15 and Dynein), the tissue inhibitor of metalloproteinase (TIMP) genes (TIMP1 and TIMP3), and MMP-9, all of which promote breast cancer cell growth, survival, and invasion." (PMID 27533254, 2016).
breast cancer (continued). "Interestingly, using unsupervised clustering analysis, this gene set (n=291) stratifies ESR1-positive and ESR1-negative breast cancer patients." (PMID 26169690, 2015). "Based on the hypothesis that IGM may play an important role in transcription, we aimed to ascertain whether IGM patterns differed in human breast cancer cells lines that were positive (n = 3) or negative (n = 3) for ESR1 expression." (PMID 25927974, 2015). "Expression of oestrogen receptor (ESR1) determines whether a breast cancer patient receives endocrine therapy, but does not guarantee patient response." (PMID 26169690, 2015). "Moreover, ESR1 mRNA level in ERα-positive breast cancer cells, such as MCF-7 and T47D does not show circadian oscillation." (PMID 24789043, 2014). "Moreover, Ingenuity network analysis of NR and CoR genes that were highly correlated with PR in breast cancers, but not normal breast, revealed an ER (ESR1)-centred network of genes." (PMID 25261374, 2014). "Similarly, a whole-genome sequencing study of 46 ER-positive, pretreatment breast cancer samples from two neoadjuvant aromatase inhibitor therapy trials [ClinicalTrials.gov:NCT00084396, ClinicalTrials.gov:NCT00265759] did not reveal any ESR1 mutations." (PMID 25928204, 2014). "Since the GDS3283 is a breast cancer data set, we selected the ChIP-seq experiments from breast cancer cell lines (T47D and MCF7 cells) to generate the regulatory TF network with Q < 0.001, which contained five significant TFs: ESR1, GATA3, FOXA1, MYC and E2F1." (PMID 24302579, 2014). "We analyzed breast cancer large sections and tissue microarrays (TMAs) using standard and RNase FISH protocols, and also employed multiplex ligation-dependent probe amplification (MLPA) after laser-capture microdissection of tumor cells as an RNA-independent means of ESR1 copy number determination." (PMID 24367641, 2013). "ER-positivity indicates the dependence of the tumor on ER-related pathways for survival and sustained growth and increased gene dosage of estrogen receptor alpha gene (ESR1), may influence the function of complex internal ER signaling pathways in breast cancer cells." (PMID 23951298, 2013). "We have extended this hypothesis assuming that ESR1 amplification, as an abnormal state, could be a negative prognostic factor in a general population of breast cancer patients as it affects the natural course of breast cancer progression." (PMID 23951298, 2013). "ESR1, which was less strongly associated with ATAD2 expression, was significant in the adjusted model only in endometrial cancer (p = 0.016) and glioblastoma (p<0.001), not in ovarian or breast cancer." (PMID 23393560, 2013). "The contact of breast cancer cell lines with the microenvironment completely modified their transcriptional programs by increasing the expression of genes involved in cell proliferation (cyclinD1, MAPK), angiogenesis (MMP9, VEGF) and hormonal pathways (ESR1, IL6)." (PMID 23750285, 2013). "Thus, we do not have strong evidence that ESR1 methylation turns off its expression in breast cancer samples, because we do not have enough points in the upper-right and lower-right quadrants." (PMID 23742247, 2013). "Hierarchical clustering analysis showed that the ESR1 ChIP datasets conducted in cells derived from uterine tissue cluster together but there was no other obvious clustering based on either the type of breast cancer cells or the length of estradiol treatment used." (PMID 24171864, 2013).
breast cancer (continued). "Also, 7 genes (CTGF, ESR1, MAPK3, PIK3R3, PLAU, PRNP, and RET) were reported to be highly relevant to growth (P<1E-04) and microtubule dynamics (P<4E-05) in tumor cell lines, and apoptosis in breast cancers (P<1E-04)." (PMID 23185353, 2012). "While at the time of diagnosis up to one-third of breast cancers are ESR1 negative, quite a few cancers that are initially ESR1 positive lose the ESR1 during the course of tumor progression and are therefore no longer responsive to endocrine therapy designed to block ESR1 function." (PMID 22414275, 2011). "Thus, although DC-SCRIPT can modulate the activity of ESR1, it does not affect the response to endocrine therapy with tamoxifen in advanced breast cancer." (PMID 21122099, 2010). "Thus, the «group query» genes ERBB2, ESR1, CEACAM5 and AR are well known markers of breast cancer." (PMID 20158879, 2010). "Interestingly, while estrogen-positive breast cancer cells seemed to be more impacted by treatment with MeG, there were no significant changes in the expression of estrogen receptor 1 or 2 and no significant impact on estrogen-dependent cancer signaling in MCF-7 cells treated with MeG (IC50)." (PMID 40733287, 2025). "Indeed, unlike human breast cancer, lower ESR1 gene expression in more aggressive CMTs does not appear to be regulated by DNA methylation and would be induced by causes that are still unknown." (PMID 36978627, 2023). "To test the potential of RMC-6272 in hormone therapy-resistant breast cancers, we utilized a MCF-7 cell line that had been continuously treated with the ER modulator tamoxifen and obtained resistance to 10 μM of tamoxifen and harbor no mutations in ESR1, the gene encoding ERα." (PMID 37264081, 2023). "However, overexpression of CaV3.2 failed to increase the expression of ESR1 in HER2-positive SKBR3 cell line (luminal type) suggesting that overexpression of CaV3.2 perhaps is not the driving force for the pathogenesis of luminal type breast cancer." (PMID 36497108, 2022). "According to histological expression of three receptor proteins, estrogen receptor (ERα; ESR1), progesterone receptor (PGR), and human epidermal growth factor receptor 2 (ERBB2; HER2; Neu), BC is divided into Luminal A, Luminal B, HER-2 positive, and triple-negative breast cancer (TNBC)." (PMID 36345017, 2022). "Invasive lobular breast carcinomas (LBCs), which account for up to 15% of all invasive breast cancers (BC), are almost always estrogen-positive (ER, coded by the ESR1 gene) and lacking HER2 amplification and as such are treated with endocrine therapy (ET)." (PMID 33353132, 2020). "Particularly, 22% of post-hormonal therapy HR+HER2- breast cancers displayed non-overlapping alterations in one or multiple effectors of MAPK signaling or in MYC or other transcription factors; these mutations were mutually exclusive with hotspot mutations in ESR1." (PMID 32210163, 2020). "Moreover, in the TCGA provisional dataset (cBioportal) there was no overlap between breast cancer biopsies overexpressing GREM1 (n = 61) or ESR1 (n = 44) mRNA (data not shown), further supporting a functional link between GREM1 expression and lack of ER-signaling." (PMID 31694641, 2019). "Therefore, the downregulation of ESR1 and PTGS2 and upregulation of ESR2 by AESN might not only provide antitumor effects against ER+ breast cancer but also afford protective effects towards the development and progression of Parkinson’s disease and Alzheimer’s disease." (PMID 31835887, 2019). "Together, these data demonstrate that PR re-expression alone is insufficient to restore ESR1 gene expression to a level comparable to wild-type cells, suggesting that the ESR1 gene is stably repressed through another mechanism once PR is absent in breast cancer cells." (PMID 30301163, 2018). "However, since very few breast cancer samples are methylated, we do not know whether methylated samples will have high ESR1 expression or low expression." (PMID 23742247, 2013).
breast cancer (continued). "Interestingly, the BRCA1 cell line MDA-MB-436, which showed lower levels of the BRCA1 transcript than those found in control breast cancer cell lines measured by quantitative RT–PCR (data not shown), had the same pattern of NFκB-related gene expression as the ESR1-negative-A tumours." (PMID 19826428, 2009). "Out of the presence or absence of three of them, ESR1 (oestrogen receptor), PGR (progesterone receptor), and HER2/ERBB2 (human epidermal growth factor receptor 2/HER2) make a breast cancer triple positive or triple negative." (PMID 40690373, 2025). "The immunohistochemical findings presented in the Human Protein Atlas (HPA) database indicated elevated levels of PIK3R1, ESR1, and AKR1C3 in breast cancer tissues as opposed to normal tissues." (PMID 39204124, 2024). "There was a non-significant difference between the ESR1 and EGFR expression levels in any breast cancer subtype." (PMID 39202273, 2024). "Therefore, estrogen deprivation therapy may not be effective in ESR1 mutant breast cancer." (PMID 39767607, 2024). "In both normal breast tissue and in breast cancer, methylation levels of the promoter regions of tumour suppressor genes such as BRCA1, BRCA2, and ESR1 were higher in both BRCA1/2 PV carriers than non-carriers." (PMID 39682099, 2024). "The hormonal-related genes studied (ESR1, CYP19A1, and PGR) were not expressed by MCF10-DCIS cancer cells that are HER2-enriched (ER−, PR−, HER2+/ERBB2+) intrinsic molecular subtypes of breast cancer." (PMID 39072314, 2024). "An RNAseq analysis of invasive breast cancer specimens from the TCGA highlighted a negative correlation between IDO1 and ESR1 gene expression, along with a significant downregulation of IDO, specifically in luminal A and B BC subtypes." (PMID 37894728, 2023). "Xpert Breast Cancer STRAT4 is a RT-qPCR platform that studies the mRNA expression of ESR1, PGR, MKI67 and ERBB2, providing a positive or negative result for each of these breast cancer biomarkers." (PMID 36980575, 2023). "To investigate this unexpectedly high incidence in more detail, we analyzed normal breast tissues of ten women without diagnosed breast cancer, 16 benign fibroadenomas and 13 ductal carcinomas in situ (DCIS) tissues, all of them ESR1-positive." (PMID 35151276, 2022). "In ER+ patient samples from TCGA breast cancer data, JMJD6 and ESR1 showed a trend towards negative correlation (Spearman, r2 = -0.23)." (PMID 36419768, 2022). "In our study, expression of ESR1 fused to exons 2 and exon 8 of CCDC170 was found in mammary epithelial tissues derived from women without diagnosis of breast cancer, and in cases with (benign) fibroadenomas, respectively." (PMID 35151276, 2022). "These top 5 H-Bs were analyzed in the other two breast cancer cell lines (BT483 and MDA-MD-231), which are ESR1-negative." (PMID 33204396, 2020). "The breast cancer biomarkers ERBB2 (HER2), ESR1(ER), PIK3CA are not significantly altered in patients with BRF2 alterations." (PMID 33176745, 2020). "Interestingly, women with ESR1 amplification in breast cancer displayed this amplification even in the benign fibrocystic breast tissue prior to the first diagnosis of cancer, and this amplification was absent in fibrocystic tissues from women who did not develop breast cancer." (PMID 31396514, 2019). "Although, PIK3CA is not found in treatment guidelines for breast cancer, as is the case for ERBB2, ESR1 or PGR, it is an oncogene found downstream ERBB2." (PMID 31169290, 2019). "Luminal-A tumors express estrogen receptor (ER/ESR1) and progesterone receptor (PR/PGR) but not HER2 receptor and accounts for 71% of the breast cancers but are slow growing and less aggressive." (PMID 30335837, 2018). "Although not a driver for ESR1 and PGR levels in SKBR3 cells, there was a strong correlation between Cav3.2 and levels of these hormone receptors in breast cancers." (PMID 27034617, 2016).
breast cancer (continued). "We then looked at the lncRNAs near ESR1, GATA3, and FOXA1 and analyzed if their expression is only coordinated in luminal breast cancer but not in basal-like breast cancer as the high expression of these genes is characteristic in luminal breast cancer." (PMID 25296969, 2014). "There was a negative correlation between ESR1 and ROBO1 in all BRCA, but positive in BRCA-Basal patients, indicating that ROBO1 could be a good complementary gene as a biomarker for breast cancer since there are few markers for BRCA-Basal cancer patients." (PMID 38137332, 2023). "Together, these data suggest that SERM or SERD influences on ERα cellular lifetime may not directly correlate with transcriptional antagonistic and anti-proliferative activities of ESR1 mutant breast cancer cells." (PMID 35575456, 2022). "We noted that ESR1, ERBB2, PIK3CAGS might not work on the whole breast cancer cohort even though they have been found to be effective in specific breast cancer cohorts." (PMID 34082714, 2021). "However, analysis of breast cancer data in the TCGA showed that levels of TRIM3 mRNA and protein did not correlate with levels of ESR1 mRNA and protein." (PMID 34508066, 2021). "However, binding of ESR1 to DNA in the absence of estrogen has been shown at specific promoters in osteoblasts and MCF-7 breast cancer cells." (PMID 33540646, 2021). "Based on our results, we conclude that the expression level of FOXA1 is significantly higher in breast cancer than in noncancerous tissues, and the effects of FOXA1 could be mediated by the ESR1 pathway." (PMID 31562808, 2019). "However, contrasting results showed that HDAC inhibition does not induce ESR1 gene expression in TNBC and even repress ESR1 in luminal breast cancer under certain conditions." (PMID 30050079, 2018). "In conclusion, changes in ESR1 and HER2 expression from primary tumor to metastasis have clearly established that breast cancer is an evolving disease and, not surprisingly, the use of CTCs to monitor treatment response on a molecular level has gained increased attention during the last few years." (PMID 28489591, 2017). "The highest ESR1 levels were observed in non-neoplastic mammary tissue and mammary hyperplasia/dysplasia in both fresh frozen and FFPE samples and the lowest in malignant mammary tumors." (PMID 27649560, 2016). "ESR1 methylation and GSTP1 methylation were not significantly correlated with poor survival in our group of male breast cancer and therefore do not seem to be useful prognostic biomarkers in male breast cancer." (PMID 22765268, 2012). "Unraveling the precise role of DC-SCRIPT in the complex genomic and non-genomic interplay between ESR1, ESR2, and their isoforms might turn out to be rewarding for elucidating the 'yin-yang' role of these factors in breast cancer." (PMID 21122099, 2010). "Although we did not directly evaluate ESR1 or PI3K/AKT gene alterations, incorporating CEACAM6 into multi-marker predictive models may enhance patient stratification and inform more personalized therapeutic approaches in HR+/HER2− breast cancer." (PMID 40936892, 2025). "However, the correlation between ESR1 and IFRD1 was non-significant in breast cancer patients." (PMID 39765744, 2024). "In contrast, overexpression of DSCAM-AS1 in T47-D cells, but not MDA-MB-231 cells, led to overexpression of ESR1, suggesting that progesterone reduces expression of DSCAM-AS1 that further suppresses expression of ESR1 to inhibit cell migration and invasion in PR-positive breast cancer cells." (PMID 36578092, 2022).